IL22 (interleukin 22)
Diseases named in the same sentence as IL22 in open-access papers (continued):
Sharing a sentence is not in itself a finding about the gene and the disease.
Obesity (continued). "Murine studies showed that exogenously administering IL-22 reversed the obesity and high-fat diet induced endoplasmic reticulum (ER) stress and pancreatic stress." (PMID 30978932, 2019). "The cumulative evidence to date suggests that IL-22 plays a role in the immune-inflammatory system in context of obesity and its metabolic consequences, but that the role of IL-22 in metabolic regulation is extremely complex and thus still controversial." (PMID 31817755, 2019). "Several mouse models of obesity also revealed beneficial effects of IL-22 treatment on glucose homeostasis, insulin sensitivity, insulin secretion and inflammation." (PMID 28143481, 2017). "In contrast to previous findings from our group and others in mouse models of obesity and type 2 diabetes, we observed little change in beta cell function after IL-22 therapy in the NOD mouse." (PMID 28779211, 2017). "The amount of IL-22 required to overcome beta cell ER stress to limit self-antigen presentation and beta cell loss in autoimmune diabetes may differ substantially from that required to contend with the low-level chronic inflammation in obesity and type 2 diabetes." (PMID 28779211, 2017). "Obesity-induced misfolding of Muc2 (as determined by Muc2 precursor staining) was reduced following treatment with the higher IL-22 dose." (PMID 27350069, 2016). "IL-22 amplifies IL-1β driven inflammation in human adipose tissue, thereby disrupting glucose homeostasis in obesity and T2DM." (PMID 27829708, 2016). "To determine the role of IL-22 in obesity and insulin resistance, we bred IL-22+/− heterozygous mice to generate wild-type littermates and IL-22KO mice." (PMID 26064446, 2015). "Here, we re-examined the effects of IL-22 on obesity, insulin resistance, and hepatic glucose metabolism." (PMID 26064446, 2015). "In the current study, we analyzed the effects of endogenous IL-22 and chronic treatment with rmIL-22 as well as genetic overexpression of IL-22 on HFD-induced obesity and metabolic syndrome." (PMID 26064446, 2015). "Numerous recent studies suggest that IL-22 modulates obesity and its metabolic consequences, but the results are inconsistent." (PMID 26064446, 2015). "As mentioned in the introduction, the effects of IL-22 on obesity and metabolic syndrome are very controversial." (PMID 26064446, 2015). "The role of IL-22 in regulating obesity and metabolic syndrome was further examined in IL-22 transgenic mice, in which IL-22 expression is controlled by albumin promoter and enhancer." (PMID 26064446, 2015). "As adipose tissue is one of the major organs involved in the regulation of metabolism, we investigated the potential effect of IL-22 overexpression in adipose tissue on obesity and insulin resistance." (PMID 21897855, 2011). "We therefore propose that the altered inflammatory status by both obesity and IL-22 overexpression contribute to WDLPS tumor formation in the mouse." (PMID 21897855, 2011). "As evidenced by the numerous studies that IPA acts as an AhR ligand to increase IL-22 secretion, we hypothesized that quercetin improved obesity through influence in IPA production and activation of AhR/IL-22 axis." (PMID 40308638, 2025). "Moreover, administration of a long-acting IL-22-Fc fusion protein and recombinant IL-22 improved IR, body weight, adiposity, and hepatic steatosis in different mouse models of obesity." (PMID 40794228, 2025). "In conclusion, quercetin supplementation restores high-fat diet induced gut microbiota dysbiosis, subsequently increasing IPA level to activate the AhR/IL-22 signaling pathway, thereby enhancing intestinal barrier integrity and attenuating chronic inflammation, which collectively ameliorate obesity." (PMID 40308638, 2025). "Elevated levels of Th22 cells and IL-22 have been observed in individuals with obesity and T2DM." (PMID 41357227, 2025).
Obesity (continued). "Specifically, quercetin ameliorated high-fat diet-induced gut microbiota disruption by reversing the reduction in Lactobacillus abundance and IPA levels, ultimately protecting gut barrier function through activation of the AhR/IL-22 pathway and alleviating chronic inflammation and obesity." (PMID 40308638, 2025). "Although not investigated in these studies, the lack of IL-22 responses to Citrobacter infection in the context of HFD-induced obesity was suggested to be due to the loss of dendritic cell IL-23." (PMID 40502773, 2025). "Thus, the IL-1R1 receptor plays a critical role in controlling intestinal homeostasis and obesity-induced MS, possibly through the differentiation or activation of IL-22-secreting ILC3s." (PMID 39203559, 2024). "IL-22 is critical for ameliorating obesity-induced metabolic disorders." (PMID 38383607, 2024). "However, the roles of ILCs are complex: some types of ILCs can promote obesity, while others show metabolic benefits through their release of proteins like IL-17 and IL-22, which can help the body to metabolise glucose." (PMID 38536726, 2024). "Emerging evidence suggests that ILC3s may regulate obesity or metabolic homeostasis through the secretion of IL-17A or IL-22." (PMID 39872860, 2023). "In addition, IL-22 therapy modulates chronic low-grade inflammation through ameliorating obesity and attenuating local inflammatory state in granulosa cells." (PMID 37525285, 2023). "Mechanistic studies have also demonstrated that reduced secretion of IL-22 was correlated with impaired glycocalyx- O-glycan in mice suffering from obesity and that such glycosylation pattern could be restored by boosting the IL-22 levels." (PMID 36613488, 2022). "IL-22-Fc treatment restores liver insulin sensitivity, decreased hepatic triglyceride and cholesterol levels, and ameliorated liver steatosis in diet-induce obesity and db/db mice." (PMID 35574038, 2022). "IL-22-associated secretion of IL-1β and IL-10 can also stimulate extracellular-signal regulated kinase (ERK) phosphorylation and promote tumor development in collaboration with diet-induced obesity." (PMID 34944732, 2021). "A Western diet is associated with a reduction in intestinal microbial species that generate AhR ligands, which ultimately might lead to the reduced levels of IL-22 that occurs in diet-induced obesity, which can, in turn, reduce intestinal barrier function." (PMID 33972511, 2021). "Cytokines produced by ILC-3 including the lymphotoxin/IL-23/IL-22 pathway may promote induction of obesity; however, IL-22 may be protective against the development of obesity." (PMID 32881912, 2020). "Further mechanistic insights of the IL-22 signaling were given in a recent studies, where indoleamine 2,3-dioxygenase 1 (IDO), an enzyme that is present in many immune cells and activated during inflammation, was linked to the gut microbiota and obesity." (PMID 33178196, 2020). "The interleukin 17 receptor E and interleukin 22 receptor subunit alpha were highly expressed in the current study, which may indicate a higher level of IL-17, due to obesity and a high level of IL-22 for protection from obesity." (PMID 32899471, 2020). "Human studies have reported on the associations of IL-22 with obesity, T2D, and cardiovascular disease, but none of these investigated dietary factors or described such associations in people with MetS." (PMID 30978932, 2019). "Interleukin-22 (IL-22) is a cytokine with important functions in host defense and inflammatory responses and has recently been suggested to play a role in immune-inflammatory system in the context of obesity and its metabolic consequences." (PMID 31817755, 2019). "Overall, IL-22 production is critical for intestinal homeostasis and may be an important therapeutic target for obesity and IR." (PMID 30944419, 2019).
Obesity (continued). "Hence, a deeper understanding of the IL-22-mediated regulation of ATM, and more refined phenotype and functional characterizations will help to delineate IL-22-mediated obesity." (PMID 31817755, 2019). "This indicates that higher levels of IL-22 could alleviate obesity-induced insulin-resistance, an important stepping stone in the development of MetS." (PMID 30978932, 2019). "The accumulation of IL-17- and/or IL-22-producing T cells is also evident in the human adipose tissue of insulin-resistant obese patients, raising the possibility that IL-22 may be involved in obesity-mediated inflammation." (PMID 31817755, 2019). "Biologically active, high levels of IL-22 do not affect obesity and the associated metabolic syndrome." (PMID 26064446, 2015). "In addition, several studies suggested that T cell-derived IL-22 enhances IL-1β-mediated inflammation in human adipose tissue and reduces insulin sensitivity in human hepatocytes, promoting obesity and diabetes." (PMID 26064446, 2015). "There were increased Th22 frequencies and IL-22 levels in obesity and T2D." (PMID 24465695, 2014). "Taken together, our study not only established a novel mouse model with spontaneous liposarcoma, but also revealed that IL-22 overexpression may collaborate with diet-induced obesity to impact on tumor development in mouse." (PMID 21897855, 2011). "Interestingly, both obesity and IL-22, two factors required for liposarcoma formation in the mouse, are associated with inflammatory response." (PMID 21897855, 2011). "Furthermore, IPA supplementation in obese mice showed that it could effectively alleviate obesity and chronic inflammation, and the improvement effect may be related to the activation of AhR/IL-22 pathway to enhance intestinal barrier function." (PMID 40308638, 2025). "In conclusion, we found that IL-1R1 is associated with a reduction in ILC3 cells in the small intestine, which may result in reduced IL-22 expression, leading to a worsening of obesity and MS due to increased intestinal permeability and bacterial translocation to the VAT." (PMID 39203559, 2024). "However, the IL-22 level varies in a number of obesity models and patients." (PMID 37525285, 2023). "The specific cellular targets and mechanisms of IL-22-mediated obesity are largely unknown however." (PMID 31817755, 2019). "However, the specific cellular targets and mechanisms of IL-22-mediated obesity remain largely unknown." (PMID 31817755, 2019). "IL-22 transgenic mice with relatively high levels of circulating IL-22 (~600 pg/ml) were completely resistant to Concanavalin A-induced liver injury but developed the same degree of high fat diet (HFD)-induced obesity, insulin resistance, and fatty liver as the wild-type littermate controls." (PMID 26064446, 2015). "Similarly, chronic treatment with recombinant mouse IL-22 (rmIL-22) protein did not affect HFD-induced obesity and the associated metabolic syndrome." (PMID 26064446, 2015). "We propose here that the inflammatory responses induced by both IL-22 overexpression and obesity could jointly contribute to the development of spontaneous liposarcomas in the mouse, although the underlying molecular mechanism still awaits detailed characterization in the future." (PMID 21897855, 2011). "Obesity results from a complex interaction between metabolic, inflammatory, microbial, and environmental factors, where REG3A and IL-22 play a partial role." (PMID 41027972, 2025). "Quercetin supplementation alleviates obesity by restoring high-fat diet induced gut microbiota disorder, which elevates IPA level to activate AhR/IL-22 pathway, thereby enhancing intestinal barrier integrity and suppressing chronic inflammation." (PMID 40308638, 2025). "In males with obesity, concentration of GRO-α was significantly lower (p<0.05) and IL-6 and IL-22 showed a lower trend in vaccinated mice." (PMID 41488663, 2025).
Obesity (continued). "There is extensive evidence of low testosterone levels observed specifically in males with obesity, MetS, and MASLD, however little data exist linking testosterone levels with the decreased hepatic IL-22 seen in these patients." (PMID 39156888, 2024). "We identifed indigo, an aryl hydrocarbon receptor (AhR) ligand agonist, as a potent inducer of IL-10 and IL-22, which protects against high-fat diet (HFD)-induced insulin resistance and fatty liver disease in the diet-induced obesity model." (PMID 30944419, 2019). "This miRNA has not been previously reported as associated with obesity, however among its targets are those involved in the pathogenesis of obesity-related complications, e.g., genes encoding interleukins (IL-6, IL-17B and IL-22), apolipoproteins (APOA5) and their receptors (APOBR)." (PMID 29280944, 2017). "Therefore, it is likely that IL-22-induced activation of ERK signaling pathway, together with the alteration of local inflammatory microenvironment impacted by both IL-22 and diet-induced obesity, may contribute to the development of spontaneous liposarcoma in the IL-22 transgenic mouse." (PMID 21897855, 2011). "Statistically, the concentrations of GROα, IL-2, IL-4, IL-6, IL-17A, IL-22, IL-23, and MCP-3 were significantly higher in males with obesity compared to the females with obesity, while the concentrations of IL-5, IL-10, IL-18, MCP-1, and MIP2α trended higher (p ≤ 0.1)." (PMID 41488663, 2025). "Supplementation with quercetin alleviates obesity by restoring the gut microbiota dysbiosis induced by HFD in obese mice, thereby increasing IPA levels to activate the AhR/IL-22 pathway, which enhances intestinal barrier integrity and suppresses chronic inflammation." (PMID 41019044, 2025). "IAA, has been reported to be produced by the flora from tryptophan metabolism and can alleviate inflammation related to alcoholic liver disease and obesity by directly or indirectly regulating the balance between proinflammatory and anti-inflammatory cytokines (TGF-β, TNF-α, IL-10, and IL-22)." (PMID 37495941, 2023). "In metabolically abnormal subjects of obesity, Fabbrini also provided evidence that increased IL-22 in serum and CD4+ T cells which produced IL-22 in adipose tissue might be related with the stimulation of cytokines such as IL-1β." (PMID 37525285, 2023). "IL-22 from ILCs and CD4+ T cells is reduced in obesity under immune challenges." (PMID 35574038, 2022). "During obesity, the pro-inflammatory skewing of immune cells favors the release of cytokines such as TNF and IFNγ, coupled with a reduction in IL-10, IL-17, and IL-22, resulting in reduced expression of epithelial tight junction proteins, mucin, and antimicrobial proteins such as RegIIIγ2,33." (PMID 33972511, 2021). "In obesity, only a few studies have investigated the role of the type 3 ILC (ILC3), but it has been hypothesized that IL-17 and IL-22 secreted from ILC3s may favor obesity and inflammation." (PMID 33572982, 2021). "A recent study extended these data to metabolic disorders and found that mice lacking IL-22 signaling are prone to obesity and insulin resistance." (PMID 28143481, 2017). "Lack of the anti-obesity effects of high levels of circulating IL-22 (600 pg/ml) in IL-22TG6 mice was very unlikely due to developing hepatic IL-22 resistance because IL-22TG6 mice were completely resistant to Con A-induced liver injury." (PMID 26064446, 2015). "This is consistent with our findings that relatively high levels of IL-22 in IL-22TG6 mice do not affect obesity." (PMID 26064446, 2015). "This suggests that very low levels of endogenous IL-22 do not contribute to the pathogenesis of obesity, insulin resistance, and fatty liver disease in the 10-week HFD feeding model." (PMID 26064446, 2015).
Obesity (continued). "Here, we provide evidence that endogenous IL-22 or biologically active, high circulating levels of IL-22 do not affect HFD-induced obesity and its metabolic consequences, although IL-22 is able to inhibit hepatic gluconeogenesis in hepatocytes." (PMID 26064446, 2015). "Interleukin-22 (IL-22), a cytokine with important functions in anti-microbial defense and tissue repair, has been recently suggested to have beneficial effects in obesity and metabolic syndrome in some but not in other studies." (PMID 26064446, 2015). "Genetic deletion of IL-22 did not affect high-fat-diet (HFD)-induced obesity and insulin resistance." (PMID 26064446, 2015). "Our results indicate that high circulating levels of transgenically expressed IL-22, chronic treatment with rmIL-22, or deficiency in endogenous IL-22 do not affect HFD-induced obesity and its metabolic consequences in mice." (PMID 26064446, 2015). "In addition, we found that IL-22TG6 mice, which have high circulating levels of IL-22 (~600 pg/ml), develop the same degree of HFD-induced obesity and its metabolic consequences as wild-type littermates." (PMID 26064446, 2015). "In summary, our findings suggest that biologically active, high levels of IL-22 do not affect obesity and its metabolic consequence." (PMID 26064446, 2015). "The IL-22 transgenic mice had no apparent changes in obesity and insulin resistance after feeding with high fat diet (HFD)." (PMID 21897855, 2011). "Overexpression of IL-22 in adipose tissue had no apparent effect on the development of obesity and changes of glucose homeostasis induced by high fat diet." (PMID 21897855, 2011). "Collectively, these data indicate that IL-22 overexpression has no apparent effect on HFD-induced obesity and insulin resistance in vivo." (PMID 21897855, 2011). "Thus, we hypothesized that quercetin mitigated HFD-induced obesity through modulation of microbial metabolite IPA, which further activated AhR/IL-22 pathway to improve intestinal barrier function." (PMID 40308638, 2025). "However, leptin does not affect the release of Il-22 from gut immune cells, and the absence of Il-22 in portal vein and systemic plasma samples of Sham rats is most likely explained by their obesity." (PMID 36992680, 2023). "Downstream activities of IL-22, such as maintaining mucosal epithelial integrity, alleviating metabolic dysfunctions, and reducing inflammation, may all contribute to the protective functions of IL-22 on NAFLD, obesity, and other metabolic syndromes." (PMID 34944732, 2021). "Given the increase in intestinal ER stress and oxidative stress as well as elevated expression of intestinal pro-inflammatory cytokines during obesity (after 22 weeks of HFD), we sought to determine whether administration of recombinant IL-22 could resolve mucosal barrier stress and inflammation." (PMID 27350069, 2016). "Thus, the very low levels of endogenous IL-22 are unlikely to contribute to the pathogenesis of HFD-induced obesity and its metabolic sequelae." (PMID 26064446, 2015). "Importantly, this phenomenon seems not to depend on the type of diet used or the duration of diet induced obesity or MASLD models, suggesting that low hepatic IL-22 levels appear stable regardless of the severity of metabolic inflammation." (PMID 39156888, 2024).